FASN (fatty acid synthase)
Diseases named in the same sentence as FASN in open-access papers (continued):
Sharing a sentence is not in itself a finding about the gene and the disease.
Obesity (continued). "To evaluate the therapeutic potential of targeting hepatic FASN for NAFLD and diabetes, we initially generated HKO and F/F mice with HFD-induced obesity." (PMID 37681411, 2023). "The goal of this study was to examine the therapeutic potential of targeting hepatic FASN for NAFLD and diabetes with the use of HKO mice with various types of obesity." (PMID 37681411, 2023). "These assays resulted in two distinct patterns for PKP2 gene expression, segregated by fat depot and the obesity state, and matching those of adipogenesis-regulated genes, such as ADIPOQ, PLIN1, and FASN." (PMID 37607954, 2023). "Further investigation of the therapeutic potential of hepatic FASN inhibition for NAFLD and diabetes in humans should thus consider the etiology of obesity." (PMID 37681411, 2023). "In total, we identified a total of 3,298 differentially expressed genes, among which we discovered key genes such as UBD, RGS2, FASN, and SCD that have functions related to adipogenesis, body weight, obesity, and lipid metabolism." (PMID 38264212, 2023). "ATF4 knockout was found to protect against diet-induced obesity, hypertriglyceridemia, and hepatic steatosis by significantly decreasing the expression of lipogenic genes, such as PPARγ, SREBP-1c, and FASN." (PMID 34237916, 2022). "Moreover, body weight regulation and obesity development may be affected by FASN." (PMID 34206460, 2021). "Higher mRNA levels of CPT1A, FASN and SREBP-1c genes in PBMC in the OW-OB group confirmed a clear impact of overweight and obesity on lipid metabolism, as we previously reported in rodents." (PMID 34526523, 2021). "PBMC mRNA levels of CPT1A, FASN and SREBP-1c increased in the OW-OB group, according with what described in liver and adipose tissue of humans with obesity." (PMID 34526523, 2021). "The blockade of fatty acid synthase (FAS) negatively regulated the HER2 expression, indicating the link between FAS activity/fat metabolism (obesity) and HER2/PEA3 expression in the malignant transformation 37-39." (PMID 33046976, 2020). "ChREBP activation in WAT is altered in obesity, resulting in the downregulation of ChREBPβ, ACLY, ACACA, FASN, and ELOVL6." (PMID 32085416, 2020). "Previously, study from our group has shown that obesity impairs the therapeutic outcome of dacarbazine (DTIC) in melanoma and induces drug-resistant phenotype by upregulating fatty acid synthase (FASN), caveolin (Cav)-1, and P-glycoprotein (P-gp)." (PMID 29568521, 2018). "In concert with the data obtained in our rodent models of obesity and insulin resistance, adipose tissue expression of other lipogenic genes, including PPARG, FASN, and SLC2A4, was lower in subjects with MAO than those with MNO." (PMID 29853530, 2018). "Fatty acid synthase (FAS) is highly expressed in human adipocytes and cancer cells and is considered as a dual therapeutic target for obesity and cancer treatment." (PMID 35542030, 2018). "Previously, we have reported that obesity impairs efficacy of DTIC in melanoma, which is mediated by FASN and Cav-1." (PMID 29568521, 2018). "In adipocytes, miR-221 contributes to the regulation of physiological network involved in fatty acid metabolism by targeting several proteins including fatty acid synthase (FASN), an enzyme overexpressed in the adipose tissue in obesity and type 2 diabetes." (PMID 26221589, 2015). "The de novo synthesis of long chain fatty acids is catalyzed by fatty acid synthase (FAS, EC 2.3.1.85), which has been considered as an anti-obesity target recently." (PMID 24341420, 2013). "Fatty acid synthase (FAS) is a key enzyme catalyzing the synthesis of fatty acid de novo, and has been considered as an anti-obesity target." (PMID 24341420, 2013). "Interestingly, we observed a significant positive correlation between ATF4 and SREBP1, FASN, and ACACA expression in PBMCs from children with obesity." (PMID 40806129, 2025).
Obesity (continued). "For FASN, boys with obesity showed higher expression than girls with obesity (p = 0.005), while girls with obesity had lower levels than girls without obesity (p = 0.017)." (PMID 40806129, 2025). "For example, EGCG has been shown to exert anti-obesity effects through AMPK activation, which triggers the downregulation of SREBP transcription factors and upregulates the expression of two lipogenic enzymes: HMGCR and FASN." (PMID 40806739, 2025). "After adjustment for sex, age, and obesity, SREBP1 expression showed negative associations with glucose homeostasis markers, whereas FASN expression was inversely associated with HDL-C." (PMID 40806129, 2025). "Notably, TA3 downregulated the expression of lipogenic factor, including fatty-acid synthase (FAS) and sterol regulatory element-binding protein 1c (SREBP1c), emphasizing its potential as an anti-obesity agent." (PMID 38474161, 2024). "Previous clinical trials have demonstrated how TRIM21 reduces de novo lipogenesis and steatosis in hepatocytes by inhibiting FASN; this mechanism is detected in patients with TRIM21, which reduces hepatic de novo lipogenesis and steatosis in patients with obesity and MAFLD and obesity." (PMID 39199424, 2024). "Remarkably, FASN is diminished in obesity, whilst FAO is elevated, indicating that obesity may encourage a metabolic shift resulting in the enhanced utilisation of lipid metabolism and FAO." (PMID 38248845, 2024). "Hepatocyte-specific ablation of FASN ameliorated NAFLD and diabetes in melanocortin 4 receptor–deficient mice but not in mice with diet-induced obesity." (PMID 37681411, 2023). "Our findings thus indicate that the therapeutic efficacy of hepatic FASN inhibition for NAFLD and T2D might be determined by the etiology of obesity, which should be taken into account in follow-up investigations in humans." (PMID 37681411, 2023). "The present study revealed a previously unknown mechanism that FASN exerted deleterious effects on lung endothelial cells, which aggravated LPS-induced ALI under obesity." (PMID 36922854, 2023). "However, FASN and LYZ were common in both approaches, suggesting an important implication of both genes in AT metabolism in lean and post-RYGB compared to obesity." (PMID 36432612, 2022). "- Anti-obesity, insulin sensitizer (↓body weight; ↓eWAT; ↓adipocyte size; ↓serum triglyceride; ↓serum insulin; ↓glucose; ↓HOMA-IR) (0.01%, 0.025% of diet, 8 weeks). - Anti adipogenesis in 3T3-L1 cells (↓C/EBPα, PPARγ, FASN, Ap2) (5, 10 μM for 48 h)." (PMID 35769384, 2022). "In addition, polyphenols and flavonoids have been proven to prevent obesity by inducing the browning of white adipose tissue (WAT) and regulating the expression of factors such as C/EBPα, SREBP-1C, ACC, and FASN, which relate to the synthesis of fatty acids." (PMID 36429320, 2022). "Obesity (BMI > 30 kg/m2), however, was associated with higher expression of FABPpm, PGC-1α and FASN in OC compared to tissue samples obtained from non-obese patients." (PMID 36012230, 2022). "Furthermore, quercetin reduces the expression of the key adipogenic factor C/EBP α and inhibits lipogenesis by downregulating the expression levels of fatty acid synthase and acetyl-CoA carboxylase in HFD-induced obesity rats." (PMID 33364948, 2020). "Inhibition of FASN and SREBP-1c expression has been reported to effectively prevent fatty acid biosynthesis, accelerate fatty acid oxidation to abolish the abnormal accumulation of FFAs, and thereby alleviate obesity and other lipid metabolism diseases." (PMID 32825154, 2020). "Moreover, we found that obesity induced lipogenesis genes in db/db mice, as demonstrated by the increased transcription of genes such as PPARγ, SREBP-1c, ACOCA, FASN, and SCD." (PMID 31246177, 2019). "The expression of FASN gene was also governed by PPARγ and involved in the facilitated conversion of FFA into TG in adipocytes, thus contributing to adipocyte hypertrophy and visceral adiposity in HFD‐fed obesity mice." (PMID 28816006, 2018).
Obesity (continued). "In our study we used orlistat, an anti-obesity drug that inhibits pancreatic lipases, and was later discovered also to irreversibly inhibit the thioesterase domain of FASN, which does not result in accumulation of cytotoxic intermediates of FA synthesis." (PMID 30148882, 2018). "Moreover, FASN inhibitors like TVB-2640, IPI-9119, GSK2194069 or Orlistat are in early research for treating obesity, cancer and other conditions, but their effects on hypothalamic pathways controlling metabolism remain unclear." (PMID 40541585, 2025). "Additionally, compound 1 (procyanidin B2) activated fatty acid oxidation regulators, PPARα and CPT1A, and suppressed fatty acid synthesis by downregulating fatty acid synthase (FAS) expression, emphasizing its potential role in modulating obesity-related markers in 3T3-L1 preadipocytes." (PMID 38613069, 2024). "Consistently, our further studies showed that the co-culture with adipocytes or treatment with PA, imitating metabolic stress in high fat diet-induced obesity, significantly elevated the expression levels of FASN in lung endothelial cells with or without LPS administration." (PMID 36922854, 2023). "Altogether, these data show that, likely in other obesity models, in childhood obesity, glucocorticoids also have permissive effects to induce hyperlipidemia and TG accumulation in the liver, probably by specific upregulation of one of the key enzymes of DNL: FASN." (PMID 37234421, 2023). "MCSFAs, such as caproic acid (6:0) and caprylic acid (8:0), have been shown in a cellular model to reduce the activity of fatty acid synthase (FAS), a primary enzyme of de novo lipogenesis that may contribute to the development of obesity and non-alcoholic fatty liver disease (NAFLD)." (PMID 36296979, 2022). "Alternatively, FASN is a crucial liver enzyme for lipid homeostasis and triglyceride synthesis, and PNPLA3 is a marker that is pathologically characterized by the regulation of lipogenesis in obesity, nonalcoholic fatty liver disease, and cardiovascular disease." (PMID 34564583, 2021). "Fatty acid synthase (FASN) is a crucial liver enzyme for lipid homeostasis and triglyceride synthesis, whereas patatin-like phospholipid domain containing protein 3 (PNPLA3) is a pathologic marker for lipogenesis regulation in obesity, nonalcoholic fatty liver disease, and cardiovascular disease." (PMID 33401717, 2021). "Finally, we also investigated the Reverse Phase Protein Arrays (RPPA) data and confirmed several reported tumor regulating proteins were differentially expressed in obesity group, including 14-3-3β, GTP-binding protein Di-Ras3 (ARHI), Fatty Acid Synthase (FASN) and ribosomal protein S6 (RPS6)." (PMID 33197880, 2020). "REV-ERB agonists could effectively inhibit the expressions of fatty acid synthase (FASN), stearoyl-CoA desaturase 1 (SCD1), and PPAR-γ coactivator 1 β (PGC-1 β) in diet-induced obese mice, in addition to decreasing fat mass, improving dyslipidemia and hyperglycemia, and reducing obesity." (PMID 40255337, 2025). "MEG3 and FTO showed sex-dependent expression in children without obesity, while additional sex-related differences were observed for SREBP1, FASN, ACACA, FTO, and MEG3 in children with obesity." (PMID 40806129, 2025). "However, previous studies suggest that global hypothalamic FASN deletion does not impair neuronal survival, as it would be incompatible with life, and POMC defiency leads to obesity-related phenotypes, arguing against major developmental disruptions in POMC neurons." (PMID 40541585, 2025). "Cells isolated from elderly subjects with or without obesity were significantly impaired in their capacity to differentiate into adipocytes, as revealed by Oil Red O staining of neutral lipids and by the gene expression of common adipogenic markers (PPARG, FABP4, LPL, PLIN1, and FASN)." (PMID 35811457, 2022).
Obesity (continued). "Therefore, the findings from this study support the idea that targeting both FASN and CD36 in combination may have therapeutic potential not only in cancer but also in metabolic disorders such as obesity and diabetes." (PMID 32850342, 2020). "In addition, the high plasma MIF levels did not alter adipogenesis gene PPARγ and FASN expression, suggesting that MIF-mediated AMPK/JNK activation in adipose tissue selectively impacted HSL and lipolysis during the development of adipocyte hypertrophy and obesity." (PMID 37935315, 2024).
prostate carcinoma (194 papers, 2005 to 2026). A carcinoma that arises from epithelial cells of the prostate gland. "Since it has been reported that a pool of FASN protein is associated with lipid microdomains in prostate cancer cells, our observation also suggests that mutation at T980 reduces this interaction." (PMID 40684943, 2025). "ERG expression is independently associated with increased FASN expression, as well as increased expression of other fatty acid metabolic genes, in prostate cancer." (PMID 38112617, 2024). "Cox analysis of hazard ratio (HR) for association of FASN protein expression with prostate cancer metastasis in combined cohorts." (PMID 38112617, 2024). "An elevated FASN expression is associated with a poor patient prognosis in colorectal cancer, and in melanoma, prostate cancer, and lymphoma, it promotes tumour growth and survival." (PMID 38610991, 2024). "In this view, it is noteworthy how the UniPR1331 treatment was able to reduce the expression of the fatty acid synthase (FASN), as the dysregulation of lipid metabolism via FASN overexpression is considered to be a hallmark of prostate cancer progression." (PMID 37895923, 2023). "Association of cross‐classified FASN/PTEN with lethal prostate cancer among men diagnosed with prostate cancer between 1983 and 2004 in the Health Professionals Follow‐Up Study and the Physicians' Health Study." (PMID 33166087, 2021). "FASN expression was associated with clinical parameters and biochemical recurrence of prostate cancer." (PMID 32655718, 2020). "For example, fatty acid synthase (FASN) is upregulated in many cancers and high level of FASN expression is associated with poor prognosis in ovarian cancer, prostate cancer, lung cancer, malignant melanoma, and sarcomas." (PMID 33064888, 2020). "Immunohistochemical staining revealed that the increased expression of FASN, RhoU and Cdc42 was associated with prostate cancer aggressiveness." (PMID 32139877, 2020). "The overexpression of FASN was reported to be linked to castration-resistant prostate cancer growth and resistance to chemotherapy." (PMID 32103349, 2020). "FASN encodes fatty acid synthase, one of the key enzymes of lipogenesis, and its inhibition has been reported to restore sensitivity to radiation in non-small cell lung and prostate cancer cells." (PMID 33255413, 2020). "Fatty acid synthase (FASN) is commonly overexpressed in prostate cancer and associated with tumour progression." (PMID 32139877, 2020). "A substantial subset of prostatic cancers displays clearly elevated expression of immunohistochemically detectable FASN, a feature that has been associated with poorer prognosis." (PMID 33194695, 2020). "FASN is associated with poor prognosis in breast and prostate cancer, and its inhibition is selectively cytotoxic to human cancer cells." (PMID 33194695, 2020). "Increased lipogenesis is observed in prostate cancer cells and is associated with their rapid growth and aggressiveness and inhibitors of fatty acid synthase (FASN) reduce cancer cell proliferation." (PMID 30774777, 2019). "Overexpression of FASN has been frequently reported in a wide variety of cancers, including breast, ovarian, endometrial and prostate cancers, and is associated with poor prognosis and resistance to chemotherapy." (PMID 29996946, 2018). "High FASN expression is associated with prostate cancer progression and is linked to higher Gleason score both at the gene and protein level." (PMID 29156692, 2017). "Preliminary results from the Uppsala Longitudinal Study of Adult Men (ULSAM) cohort showed that men with higher levels of fatty acid synthase (FASN) had an increased risk of prostate cancer death compared to patients with normal levels (unpublished data)." (PMID 28732480, 2017). "Overexpression of fatty acid synthase (FASN) in breast and prostate cancer is associated with the poor prognosis and inhibition of FASN attenuates the lipogenesis and serves as the therapeutic approach." (PMID 27171439, 2016).